GLCCI1 (glucocorticoid induced 1)
Synonyms: GIG18; FAM117C; TSSN1; GCTR
Tractability: PROTAC: ubiquitination databases record sites on it; its protein half-life has been measured.
Gene: Protein-coding gene on chromosome 7 (7,968,796 to 8,094,272, forward strand). Ensembl gene ENSG00000106415.
Subcellular location (Human Protein Atlas): Nucleoli
Gene Ontology:
Molecular function: protein binding
Biological process: cellular response to glucose stimulus
Cellular component: cytoplasm; podocyte foot
Genetic constraint (gnomAD): Loss-of-function variants: 20 observed, 32.66 expected, observed/expected ratio (o/e) 0.61, 90% interval 0.43 to 0.89. The synonymous counts are far from expectation, so gnomAD's model fits this gene poorly and the ratio says little. Missense variants: 519 observed, 465.12 expected, observed/expected ratio (o/e) 1.12, 90% interval 1.04 to 1.2. Synonymous variants: 227 observed, 176.54 expected, observed/expected ratio (o/e) 1.29, 90% interval 1.15 to 1.43.
Homologues: Orthologues: chimpanzee GLCCI1 (99% identical), macaque GLCCI1 (98% identical), pig GLCCI1 (96% identical), rat Glcci1 (92% identical), mouse Glcci1 (92% identical), dog GLCCI1 (75% identical), guinea pig GLCCI1 (63% identical), tropical clawed frog glcci1 (61% identical), zebrafish glcci1a (54% identical). Paralogues in human: FAM117B (49% identical), FAM117A (31% identical).
Diseases named in the same sentence as GLCCI1 in open-access papers:
GLCCI1 is named in the same sentence as 14 diseases in open-access papers, as found by Europe PMC text mining. Sharing a sentence is not in itself a finding about the gene and the disease. The quoted sentences say what the papers report.
asthma (22 papers, 2013 to 2024). "In our previous study, we found that GLCCI1 expression levels are related to the risk of asthma, with GLCCI1 acting as a protective factor against the condition." (PMID 39834584, 2024). "Specifically, Tantisira et al2 reported that a mutation leading to decreased expression of GLCCI1 can alter the biological effects of glucocorticoids in patients with asthma." (PMID 39834584, 2024). "The expression of the GLCCI1 gene was detected in lung tissue and in immune cells and the association of rs11976862*GG genotype of the GLCCI1 gene with asthma in Chinese asthma patients using ICS were revealed." (PMID 39795959, 2024). "The glucocorticoid-induced transcript 1 (GLCCI1) gene has garnered significant attention in asthma research due to its association with the glucocorticoid response, a cornerstone of asthma treatment." (PMID 39834584, 2024). "Glucocorticoid-induced transcript 1 (GLCCI1) has been reported to be associated with the efficiency of inhaled glucocorticoids in patients with asthma." (PMID 39834584, 2024). "GLCCI1 has been identified as a functional variant that plays an important role in the development of asthma as well as in drug efficacy." (PMID 37157161, 2023). "This meta‐analysis suggests that the GLCCI1 rs37973 variant had significant influence on ICS therapy in patients with asthma." (PMID 37157161, 2023). "Genetic polymorphism in the GLCCI1 gene, including its promoter region, has been associated with glucocorticoid response in asthma patients, pediatric nephrotic syndrome, and Graft-versus-Host disease." (PMID 37900285, 2023). "In summary, the GLCCI1 (rs37973 G > A) variant affects the efficacy of ICS in the treatment of asthma, and the results of this study provide a theoretical basis for the use of the rs37973 variant as a predictor of the efficacy of ICS in asthma patients." (PMID 37157161, 2023). "In conclusion, the present meta‐analysis demonstrates that the GLCCI1 (rs37973 G > A) variant affected the efficacy of ICS in the treatment of asthma." (PMID 37157161, 2023). "To ascertain the mechanisms underlying GLCCI1-mediated regulation of the effects of GCs on chemokines, we began by assessing asthma-related pro-inflammatory chemokines (CCL2, CCL3, CCL4, and CCL7) in lung tissues by RT-PCR." (PMID 34504850, 2021). "This project determines the underlying mechanism that GLCCI1 deficiency attenuates GC sensitivity in dexamethasone (Dex)-treated Ovalbumin (OVA)-induced asthma mice and epithelial cells through upregulating binding of IRF1:GRIP1 and IRF3:GRIP1." (PMID 34504850, 2021). "The aim of our study is to investigate the effects of STIP1 and GLCCI1 polymorphisms on the risk of childhood asthma and ICS response in Chinese asthmatic children." (PMID 33208131, 2020). "Single nucleotide polymorphisms in the GLCCI1 gene, encoding the glucocorticoid-induced transcript 1 protein, were associated with response to GC therapy in asthma." (PMID 32911071, 2020). "In a Saudi Arabian study, 2 GLCCI1 SNPs, (rs37972 and rs37973), were found to be unrelated to adult asthma susceptibility." (PMID 33208131, 2020). "In conclusion, we found significant associations between the STIP1 rs2236647 polymorphism and the risk of childhood asthma, and GLCCI1 SNPs are related to the improvement of lung function in Chinese Han childhood asthma patients who received ICS for 3 months." (PMID 33208131, 2020). "STIP1 rs2236647 was associated with asthma risk of children and GLCCI1 rs37969 mutant genotypes were associated with less improvement in airway hyper-responsiveness." (PMID 33208131, 2020). "SNPs in GLCCI1 in patients with asthma have been associated with a decreased response to inhaled glucocorticoids." (PMID 27688786, 2016). "GLCCI1 deficiency promotes asthma inflammation through PI3K-induced NLRP3 inflammasome activation." (PMID 39834584, 2024).
asthma (continued). "Glucocorticoid‐induced transcript 1 (GLCCI1), an early marker of glucocorticoid‐induced inflammatory cell apoptosis, is associated with asthma susceptibility and glucocorticoid efficacy and is an important gene in the process of glucocorticoid‐promoted inflammatory cell apoptosis." (PMID 37157161, 2023). "Increased IRF1 and IRF3 expression might take part in GLCCI1 deficiency-induced GC insensitivity in asthma." (PMID 34504850, 2021). "Given the hypothesized link between asthma pathogenesis and autophagy, we sought to identify whether the autophagy‐promoting gene products of WD repeat domain 45B (WDR45B) were involved in GLCCI1 modulation of asthma susceptibility and treatment response." (PMID 34050597, 2021). "A GWAS study indicated that GLCCI1 rs37972 polymorphism was associated with ICS response in white childhood asthma patients and replicated their findings in three adult clinical trials and a Network childhood asthma trial (Data from the database of Genotypes and Phenotypes, dbGaP)." (PMID 33208131, 2020). "A recent study indicated that GLCCI1 variants (rs37972 and rs37973 polymorphisms) could serve as asthma risk biomarkers in a Tunisian adult population." (PMID 33208131, 2020). "GLCCI1 rs37969, rs37972 and rs37973 polymorphisms might be associated with pulmonary function in childhood asthma patients after ICS treatment." (PMID 33208131, 2020). "Our findings revealed a significant decrease in Glcci1 mRNA levels in induced sputum from patients with asthma compared with healthy controls." (PMID 39834584, 2024). "This indicates that GLCCI1 expression in macrophages is crucial for enabling PI3K inhibitors to decrease asthma symptoms." (PMID 39834584, 2024). "In this study, we observed an inverse relationship between IL-1β levels and GLCCI1 mRNA levels in sputum from patients with asthma." (PMID 39834584, 2024). "The expression levels of genes encoding GLCCI1, NLRP3 inflammasome components, and PI3K pathway-related indicators were detected in cells isolated from induced sputum from patients with asthma and healthy controls." (PMID 39834584, 2024). "We searched the PubMed, Embase, Cochrane Library, CBM, CNKI and Wanfang databases to obtain studies on the GLCCI1 rs37973 variant and the efficacy of ICS in asthma." (PMID 37157161, 2023). "In a mouse model of asthma GLCCI1 was shown to play a role in airway remodeling by modulating inflammatory signaling." (PMID 37900285, 2023). "Recently, WDR45B was found to improve airway remodeling and reduce collagen deposition and airway hyperreactivity in mouse asthma models, by means of combining with glucocorticoid induced 1 (GLCCI1) to inhibit the autophagy activation effect of GLCCI1." (PMID 36900050, 2023). "Based on the findings of this study, detecting the genotype of GLCCI1 rs37973 (G > A) is necessary for patients with asthma who use ICS." (PMID 37157161, 2023). "Another glucocorticoid-induced gene, GLCCI1, is considered to be a new pharmacogenetic determinant of asthma patient responses to ICS." (PMID 35600871, 2022). "Both hydroprednisone therapy and glucocorticoid-induced transcript 1 (GLCCI1) overexpression repressed the airway remodeling in asthma mice model via suppressing IL-13/periostin/TGF-β1 axis." (PMID 36611844, 2022). "Current studies have focused on asthma, where GLCCI1 gene variability is related to a noticeable decline in response to inhaled glucocorticoids in asthmatic patients." (PMID 35935867, 2022). "In this present study, we explored the mechanism of GLCCI1 in regulating asthma development through activation autophagy via binding with WDR45B." (PMID 34050597, 2021). "Increasing of WDR45B in vivo reversed the improvement of GLCCI1 on airway remodelling in asthma and the inhibition to autophagy level in lung tissues." (PMID 34050597, 2021).
asthma (continued). "The aim of this study was to explore the function of GLCCI1 expressed on epithelial cells in regulating GC responses via the GR-GRIP1 pathway in an Ovalbumin (OVA)-induced asthma model." (PMID 34504850, 2021). "According to new insight into the significance of epithelial cells in GC sensitivity in asthma and the high level of GLCCI1 expression in epithelial cells, we chose to continue exploring the detailed mechanism of GLCCI1 in GC function in epithelial cells." (PMID 34504850, 2021). "We previously demonstrated the tendency for a decreased hydroprednisone response in GLCCI1−/− mice with OVA-induced asthma when compared with WT mice with OVA-induced asthma." (PMID 34504850, 2021). "Glucocorticoid-induced transcript 1(GLCCI1) also plays a key role in steroid biology and involved essentially in asthma signaling." (PMID 33208131, 2020). "It is worth mentioning that we are the first to report the function of STIP1 rs2236647 and GLCCI1 rs37969 in childhood asthma patients and more studies are required to repeat our findings." (PMID 33208131, 2020). "We also report here that GLCCI1 rs37969, rs37972, and rs37973 were associated with the response to ICS treatment in Chinese children with asthma." (PMID 33208131, 2020). "SNPs within the GLCCI1, T gene, and FBXL7, were associated with ICS response in pediatric asthma populations and were conducted by the same research group." (PMID 30647901, 2019). "SNPs within GLCCI1, T gene, and ALLC were associated with changes in the lung function and rs10044254 SNP within FBXL7 was associated with changes in the asthma symptom scores." (PMID 30647901, 2019). "GLCCI1 was identified as a novel pharmacogenetic determinant of the response of asthma patients to inhaled corticosteroid." (PMID 27852250, 2016). "Considering the strong ability of activated macrophages to secrete inflammatory cytokines like IL-1β, using PI3K inhibitors could potentially reduce asthma symptoms by boosting the protective effects of GLCCI1 in these cells." (PMID 39834584, 2024). "Moreover, we recently reported decreased methylation of GLCCI1 in peripheral blood mononuclear cells from patients with asthma and showed that multiple GLCCI1 CpG methylation sites are positively correlated with GLCCI1 expression." (PMID 39834584, 2024). "The GLCCI1 rs37973 mutation inhibits GLCCI1 transcription in non-Hispanic Caucasian patients with asthma, which is related to inhaled corticosteroid (ICS) efficacy." (PMID 39834584, 2024). "By comprehensively evaluating the interplay between GLCCI1, the PI3K pathway, and NLRP3 inflammasome activation in macrophages, our study provides further insights into the molecular mechanisms underlying the pathogenesis of asthma." (PMID 39834584, 2024). "In order to explore whether GLCCI1 affects macrophages in the context of asthma, we performed macrophage depletion and adoptive transfer experiments." (PMID 39834584, 2024). "Given the established significance of these pathways in asthma-related inflammation, the aim of our study was to determine whether GLCCI1 modulates airway inflammation through its involvement in the PI3K pathway and in NLRP3 inflammasome activation." (PMID 39834584, 2024). "Therefore, this study conducted a meta‐analysis of the correlation between the GLCCI1 rs37973 variant and the efficacy of ICS in the treatment of asthma, providing a theoretical basis for the clinical application of ICS in drug therapy for asthma patients." (PMID 37157161, 2023). "GLCCI1 plays a significant role in modulating glucocorticoid (GC) sensitivity in asthma." (PMID 34504850, 2021). "Overall, our data indicated that GLCCI1 could effectively improve the airway remodelling in ovalbumin‐sensitized mice through inhibiting asthma‐induced autophagy via combination with WDR45B and suppressing its expression." (PMID 34050597, 2021).
asthma (continued). "Our own previous data showed that GLCCI1 variations are associated with asthma susceptibility and the ICS response in the adult Chinese Han population and that GLCCI1 expression might be affected by variations in GLCCI1 during the ICS response period." (PMID 34504850, 2021). "The present project confirms that the loss of GLCCI1 expression leads to GC insensitivity through downregulating the GR-GRIP1 pathway, which is associated with the increased interaction between IRF1 and GRIP1 and between IRF3 and GRIP1 in asthma." (PMID 34504850, 2021). "Above studies have suggested that GLCCI1 may play a crucial role in the development of asthma, while the mechanism of how GLCCI1 influences asthma development remains unclear." (PMID 34050597, 2021). "Here, we explored the role and action mechanism of GLCCI1 in asthma development." (PMID 34050597, 2021). "However, in a study we performed in 82 Turkish children with moderate-severe asthma exacerbation, we were unable to show any association between FEV1 increase after 4 h of single-high-dose ICS and variation at GLCCI1 rs37973, rs3099266, rs2305089 genotypes." (PMID 30647901, 2019). "The GLCCI1 gene has been ascribed a role in the sensitivity of various tissues to glucocorticoids, initially thymoma cell lines and recently in the degree of response to glucocorticoid therapy in asthma." (PMID 23836780, 2013). "GLCCI1 may serve as an early marker of GC-induced apoptosis, which is a key mechanism by which GCs alleviate lymphocytic and eosinophilic inflammation in asthma." (PMID 39769372, 2024). "The results of this study suggested that patients carrying the G allele may exhibit reduced ICS therapeutic efficacy after ICS administration and that the analysis of GLCCI1 (rs37973 G > A) in asthma patients will help provide a scientific guidance for the clinical use of ICS." (PMID 37157161, 2023). "Therefore, GLCCI1 expressed on epithelial cells plays a crucial and important role in mediating the GC response in asthma, which might be beneficial for bio-identification, but the potential mechanism is not very clear." (PMID 34504850, 2021). "Therefore, our study in Chinese Han childhood asthma population support the perspective that GLCCI1 might be considered as a predictor of ICS response to a certain extent." (PMID 33208131, 2020). "Additionally, the level of GLCCI1, which is significantly associated with the response of asthma patients to inhaled glucocorticoids, was not affected by DEX in neutrophils from asthmatics." (PMID 27852250, 2016). "A recent study analyzing gene and microRNA expression levels in peripheral blood T cells from patients with severe asthma treated with benralizumab showed a correlation between the PI3K pathway and GLCCI1." (PMID 39834584, 2024). "To investigate the role of GLCCI1 in regulating the PI3K pathway, we generated an OVA-induced asthma model using both WT and Glcci1-/- mice and evaluated airway inflammation following treatment with LY294002." (PMID 39834584, 2024). "We then explored the relationship between GLCCI1 and both the PI3K pathway and NLRP3 inflammation in patients with asthma." (PMID 39834584, 2024). "However, there have been no reports indicating whether GLCCI1 deficiency in patients with asthma contributes to enhanced airway inflammation through activation of the PI3K pathway or activation of the NLRP3 inflammasome." (PMID 39834584, 2024). "Next, we induced asthma in wild-type C57BL/6 mice and Glcci1 knockout (Glcci1-/-) mice by injecting them with ovalbumin (OVA) and treated the asthmatic mice with a PI3K pathway inhibitor (LY294002) or left them untreated." (PMID 39834584, 2024). "Glucocorticoid-induced transcript 1 (GLCCI1) is expressed in both lung cells and immune cells, and its expression is significantly enhanced by the presence of glucocorticoids in asthma-like conditions." (PMID 27852250, 2016).
asthma (continued). "Some of the genes that are worth highlighting include GLCCI1, whose links with a poorer response to ICS in asthma patients have been replicated in different populations, and FCER2, with a variant associated with asthma exacerbations and poor lung function despite ICS use in two independent cohorts." (PMID 39769372, 2024). "Therefore, it is necessary to further explore the relationship between GLCCI1 and the PI3K pathway in asthma." (PMID 39834584, 2024). "This could point to a possible functional link between GLCCI1 and DYRK1A in asthma, and further characterization of the role of DYRK1A in the GLCCI1 function could potentially lead to new avenues in asthma research." (PMID 37900285, 2023). "There was no significant change in the level of GLCCI1 in neutrophils treated with DEX from SS asthma and SR asthma patients." (PMID 27852250, 2016). "There was no statistically significant significance in the level of GLCCI1 in SS and SR asthma neutrophils treated with DEX or asthmatic serum/DEX." (PMID 27852250, 2016). "An deficiency of GLCCI1 in macrophages significantly reduced the ability of LY294002 to suppress NLRP3-mediated inflammation, reinforcing the idea that a signaling pathway involving PI3K, GLCCI1, and NLRP3 may shape macrophage function in the context of asthma." (PMID 39834584, 2024). "However, the specific mechanisms by which GLCCI1 dificiency exacerbates airway inflammation in asthma have not yet been fully elucidated." (PMID 39834584, 2024). "In addition, another study found that GLCCI1 rs37973 did not influence the treatment response to ICS in white asthma patients." (PMID 37157161, 2023). "In short, global GLCCI1 knockout in Dex-treated asthmatic mice could reduce GR and GRIP1 expression, decreasing the less binding of GRIP1 to GR, which finally reduced Dex anti-inflammatory responses and led to GC insensitivity in asthma." (PMID 34504850, 2021). "The current data on GLCCI1 rs37969 is extremely lacking, especially in childhood asthma." (PMID 33208131, 2020). "However, in vitro and/or in silico analyses provide additional evidence that genes discovered in these GWAS (e.g. GLCCI1, FBXL7, T gene, ALLC, CMTR1) might play a direct or indirect role in asthma/treatment response pathways." (PMID 30647901, 2019). "Here we examined the expression of GLCCI1 mRNA in response to DEX with or without asthmatic serum in neutrophils isolated from SS and SR asthma patients." (PMID 27852250, 2016). "Similarly, the levels of GLCCI1 were not affected by DEX/asthmatic serum combination in SS asthma and SR asthma patients." (PMID 27852250, 2016).
acute GVHD (1 paper, 2025). "In univariate analyses, donor GLCCI1 rs37973 AG/AA genotypes were associated with a higher incidence of grades II to IV acute GVHD but a lower incidence of chronic GVHD compared with GG donors." (PMID 41264074, 2025).